TERT (telomerase reverse transcriptase)
Diseases named in the same sentence as TERT in open-access papers (continued):
Sharing a sentence is not in itself a finding about the gene and the disease.
neuroblastoma (continued). "Induction of TERT occurs in the majority of high-risk neuroblastomas, and telomerase has thus been considered as a promising tractable target." (PMID 35953764, 2022). "TERT expression has been suggested to be a key molecular feature in neuroblastoma, and increased TERT expression has been associated with MYCN amplification." (PMID 36175618, 2022). "The EUH subset includes (i) MYC-driven neuroblastoma expressing high MYC and/or MYCN protein, (ii) Neuroblastoma with TERT overexpression due to genomic rearrangements, and (iii) Neuroblastoma of the ALT group due to ATRX loss." (PMID 33968044, 2021). "In neuroblastoma, translocation of enhancer regulatory elements near the promoter was previously associated with TERT upregulation." (PMID 32024823, 2020). "Amplification of the MYCN oncogene is found in almost 40% of clinical high-risk neuroblastomas, and is associated with up-regulation of TERT expression and telomere dysfunction." (PMID 32375866, 2020). "The TERT rearrangements occur mainly in high-risk neuroblastoma in mutually exclusiveness with MYCN amplifications and ATRX mutations." (PMID 32121056, 2020). "Amplification of the proto-oncogene MYCN, a known transcriptional activator of TERT, occurs in roughly 20% of primary neuroblastomas and is a well-established marker for defining high-risk disease." (PMID 31757062, 2019). "TERT mutations were found on whole genome sequencing in high risk neuroblastoma, although these only occurred in the absences of ATRX mutations or MYCN amplification." (PMID 30154341, 2018). "Driver genes/alterations, such as MYCN, 1p/11q deletion, ALK, ATRX and TERT, are characterized in high-risk neuroblastoma by previous studies, however, it is difficult to further stratify the high-risk neuroblastoma at molecular level." (PMID 30405689, 2018). "As well as MYCN amplification (MNA), high risk neuroblastomas have also been shown to elevate telomerase reverse transcriptase (TERT) expression through deregulatory genomic rearrangements." (PMID 29505958, 2018). "Increased expression of TERT is associated with certain tumors and telomerase activation through abrogation of transcriptional silencing of TERT can lead to the development of high-risk cancers such as neuroblastoma." (PMID 28686177, 2017). "A recent analysis on structural variants using whole genome sequencing revealed that TERT promoter rearrangements characterize a subgroup of high-risk neuroblastoma with poor prognosis comparable to MYCN amplified tumors." (PMID 28521285, 2017). "TERT rearrangements are a common genetic alteration in high-risk neuroblastomas and are associated with increased TERT expression and a poor prognosis." (PMID 29312603, 2017). "In neuroblastoma, researchers observed that several super‐enhancers can translocate proximal to the TERT gene, which encodes for telomerase reverse transcriptase, causing TERT overexpression." (PMID 39853740, 2026). "Liquid biopsy–based detection of the patient-specific TERT rearrangement breakpoints mirror the presence of disease in individual patients, indicating the potential for this assay to monitor disease in patients with high-risk and very high-risk neuroblastomas harboring TERT rearrangements." (PMID 39760332, 2025). "However, TERT rearrangements combined with mutations in the RAS/MAPK/ALK signal transduction network define a very high-risk neuroblastoma subgroup with a particularly poor patient outcome." (PMID 39760332, 2025). "Most high-risk neuroblastomas exhibit high levels of telomerase activity, which are caused by induction of the telomerase reverse transcriptase (TERT) gene through MYCN over-expression in MYCN-amplified tumors, or through genomic rearrangements of the TERT locus." (PMID 35953764, 2022).
neuroblastoma (continued). "In an additional 23–31% of high-risk neuroblastomas, TERT is activated through chromosomal rearrangements involving 5p15.33, proximal to the TERT gene, which induces transcriptional up-regulation of TERT by juxtaposing the TERT coding sequence with strong enhancer elements." (PMID 32375866, 2020). "Moreover, the methods we applied are not appropriate to detect copy number neutral structural variations known to cause TERT alterations in human neuroblastoma." (PMID 29492199, 2018). "In addition, rearrangements at the TERT promoter which appose super-enhancers to the TERT gene have been found to mediate TERT reactivation in high-risk neuroblastoma." (PMID 28264499, 2017). "The 1 ng DNA spike-in was also sufficient to quantify TERT gene copy number, demonstrating that GI-ME-N cells belong to the rare cases in the panel of 16 neuroblastoma cell lines analyzed that harbored a TERT copy number gain." (PMID 39760332, 2025). "Reanalysis of whole-genome and targeted panel sequencing data from 169 patients identified 64 TERT-rearranged neuroblastoma samples collected at initial and/or relapse diagnosis from 55 patients (254 total TERT rearrangement events)." (PMID 39760332, 2025). "ATRX and TERT mutations are more commonly found in patients older than the age of 18 months, with TERT being associated with stage 4 disease and ATRX being associated with a refractory clinical subtype – all of which are unfavourable signs of neuroblastoma." (PMID 40653949, 2025). "The corresponding mononuclear cell fraction of every BM sample was also analyzed to directly determine the TERT breakpoints in neuroblastoma cells metastasized to the BM niche." (PMID 39760332, 2025). "We initially reanalyzed bulk sequencing data from a cohort of 169 neuroblastoma tumor samples to detect the number of neuroblastomas harboring TERT rearrangements." (PMID 39760332, 2025). "Here, we used these data to comprehensively examine the epigenetic regulation of the TERT promoter region in neuroblastomas." (PMID 38837897, 2024). "Here, we leveraged our extensive neuroblastoma epigenetic database to understand how the TERT promoter is regulated in neuroblastoma." (PMID 38837897, 2024). "Taken together, these data suggest that epigenetic regulation of TERT expression differs in neuroblastoma depending on the telomere maintenance status, and H3K27 methylation is important in repressing TERT expression in neuroblastoma with long telomeres." (PMID 38837897, 2024). "Using MYCN ChIP-seq data as well as qRT-PCR and reporter assays, we showed that TERT is a bona fide MYCN target in neuroblastoma cells." (PMID 38837897, 2024). "Strikingly, in neuroblastoma with long telomeres, the hypomethylated region spans the entire TERT locus, including multiple nearby genes with enrichment for the repressive H3K27me3 chromatin mark." (PMID 38837897, 2024). "When we stratified the neuroblastoma cell lines by short versus long telomeres, a striking pattern emerged when we evaluated the methylation status of the TERT promoter CpG island." (PMID 38837897, 2024). "MYCN-amplified neuroblastoma (MNA neuroblastoma) represents about half of poor prognosis neuroblastoma, with the remainder attributable to enhancer alterations leading to over-expression of TERT or MYC." (PMID 39313128, 2024). "We here systematically characterized the effects of copy-number dosage on neuroblastoma gene expression and demonstrated how copy-number gains interact with upregulated TERT to increase the efficacy of CTM." (PMID 39635126, 2024). "Overall, these findings reveal new insights in the epigenetic regulation of the TERT promoter in neuroblastoma." (PMID 38837897, 2024). "In conclusion, we show that the TERT region is differentially regulated in neuroblastoma cells depending on the mechanism of telomere maintenance." (PMID 38837897, 2024).
neuroblastoma (continued). "TERT expression was consistently elevated in neuroblastoma cell lines with short telomeres, while neuroblastoma cell lines with long telomeres had extremely low levels of TERT." (PMID 38837897, 2024). "EZH2 inhibition facilitated MYCN binding to the TERT promoter in neuroblastoma cells with long telomeres." (PMID 38837897, 2024). "The TERT promoter in telomerase-positive neuroblastoma cell lines showed enrichment for both the repressive mark H3K27me3 and the active mark H3K4me3." (PMID 38837897, 2024). "In neuroblastomas with long telomeres, the hypomethylated region extended beyond the proximal promoter region to include the entire TERT locus, and multiple nearby genes." (PMID 38837897, 2024). "MYCN is a transcription factor that induces transcriptional and epigenetic reprograming and MYCN-amplified neuroblastoma cells express TERT." (PMID 38837897, 2024). "Taken together, these observations suggest that epigenetic factors play an important role in telomere maintenance and the modulation of TERT expression in neuroblastoma." (PMID 38837897, 2024). "TERT was frequently placed in juxtaposition to a previously established gene in neuroblastoma tumorigenesis or cancer in general." (PMID 38136279, 2023). "The most highly mutated genes, such as MYC, TERT, FASLG, RIPK1, TNFSF10, TARDBP, and CDKN2A, have been well characterized in liver cancer, diffuse large B-cell lymphoma, neuroblastoma, and kidney renal clear cell carcinoma." (PMID 35875102, 2022). "For those patients with TERT-overexpressing neuroblastoma, clinical trials with telomerase inhibitors can be considered." (PMID 35053227, 2022). "Another recent study demonstrated anticancer effects of the BET bromodomain inhibitor OTX015 and the proteasome inhibitor carfilzomib by TERT down-regulation in TERT-rearranged neuroblastoma cell lines." (PMID 35953764, 2022). "Median expression of TERT in Wilms tumor was found to be between the two modes of TERT expression seen in neuroblastoma and medulloblastoma, which have bimodal TERT expression according to the tumor molecular subtype." (PMID 35406427, 2022). "Based on RNA sequencing data of a larger neuroblastoma cohort, a threshold for high versus low TERT expression was defined according to the definition of a threshold that had been used previously." (PMID 36153564, 2022). "MBD2 has been proven to significantly inhibit the expression of telomerase reverse transcriptase (TERT) via binding the hypermethylated region of the TERT promoter in liver, breast, cervical, and neuroblastoma cell lines." (PMID 35051313, 2022). "In support of an oncogenic role for TERT, neuroblastoma cell lines having rearrangements or MYCN amplification exhibited both upregulated TERT expression and enzymatic telomerase activity." (PMID 34796286, 2021). "Telomerase activation is commonly observed in high-risk neuroblastoma, such as MYCN-amplified tumors and TERT-rearranged tumors." (PMID 34885007, 2021). "In line with a heterochromatic enrichment, protein expression of the demethylase KDM1A responsible for removing methyl groups from H3K9me337 was significantly lower in ALT-positive neuroblastomas compared to TERT-activated tumors." (PMID 33627664, 2021). "Lower expression of TERT was observed in stage 4S compared with stage 4 tumors indicating that TERT DNA methylation also regulates telomerase activity in stage 4S neuroblastoma." (PMID 34796286, 2021).
neuroblastoma (continued). "TERT rearrangements were detected in 3 out of 20 neuroblastomas, and ATRX alterations were detected in 4 neuroblastomas (2 SNV and 2 losses)." (PMID 34442335, 2021). "In line, we detected 29 MYCN-amplified neuroblastomas, but also 42 TERT rearrangements and 8 ATRX alterations." (PMID 34442335, 2021). "To detect alterations associated with telomere maintenance, a crucial mechanism of neuroblastoma tumor biology, we selected probes to detect ATRX mutations or deletions, as well as TERT rearrangements." (PMID 34442335, 2021). "Another mechanism of TERT upregulation, observed in neuroblastoma, comprises genomic rearrangements affecting the TERT locus at 5p15.33." (PMID 32121056, 2020). "The comprehensive genome-wide analysis performed here allowed us to discover age-associated alterations in MYCN, TERT, PTPRD, and Ras pathway alterations, which together with ATRX represent the majority of common driver gene alterations in neuroblastoma." (PMID 33056981, 2020). "The majority of high-risk neuroblastomas can be divided into three distinct molecular subgroups defined by the presence of MYCN amplification, upstream TERT rearrangements or alternative lengthening of telomeres (ALT)." (PMID 32375866, 2020). "In neuroblastoma cells, we observed that the TERT gene was typically amplified in double-minuses, and each cell harbored more than 100 TERT copies." (PMID 31285550, 2019). "Chromothripsis events on chromosomes 2, 5, and 17 in neuroblastoma tumors have been previously reported to be associated with MYCN amplification, TERT rearrangements, and 17q gain, respectively." (PMID 31693904, 2019). "Recent large parallel sequencing studies in neuroblastoma have identified TERT rearrangements, resulting in abnormal telomerase activity, to be involved in telomere maintenance." (PMID 30326621, 2018). "Additional studies have demonstrated that down regulation of TERT inhibits proliferation and invasion of neuroblastoma cells and promotes apoptosis." (PMID 30326621, 2018). "An additional study of 217 neuroblastoma cases found TERT rearrangements in 13% of tumors, all but one, stage 4 patients with high-risk disease." (PMID 30326621, 2018). "TERT mRNA expression in neuroblastoma cases was first detected in 2004; in that cohort, all cases with TERT expression had poor prognosis and were correlated with MYCN expression." (PMID 30326621, 2018). "Aberrant high expression of TERT due to intragenic rearrangements were frequently found in aggressive phenotype of neuroblastoma." (PMID 29296183, 2017). "Subcellular shuttling of TERT protein from the nucleus to mitochondria has been reported in different cell types, including human cervical cancer, human neuroblastoma and human breast adenocarcinoma cells." (PMID 28765565, 2017). "We were interested whether the genomic breakpoints of TERT rearrangements have sequences that are unique to the neuroblastoma or metastases in a single patient, thus presenting precise target sequences capable of monitoring disease in serial liquid biopsies." (PMID 39760332, 2025). "TERT-rearranged neuroblastoma cases are routinely identified by break-apart FISH." (PMID 39760332, 2025). "This is a novel liquid biopsy–based in-time monitoring concept for infants and children with TERT-rearranged neuroblastoma with and without additional mutations in the RAS/MAPK/ALK signaling network." (PMID 39760332, 2025). "Notably, MYCN was enriched at the TERT promoter in MYCN-amplified neuroblastoma cells (SKNBE2, NB5)." (PMID 38837897, 2024). "We examined the chromatin marks at the TERT locus and found that neuroblastoma cells with MYCN amplification and short telomeres are enriched for chromatin marks indicative of open chromatin including H3K4me3, H3K27Ac, H3K14Ac, RNA PolII, and BRD4 at the TERT promoter." (PMID 38837897, 2024).
neuroblastoma (continued). "Interestingly, we also observed that inhibiting EZH2 derepressed TERT and induced expression in neuroblastoma cells with long telomeres, relative to the housekeeping gene HPRT." (PMID 38837897, 2024). "In contrast, the TERT gene body is hypermethylated in telomerase-positive neuroblastoma cells." (PMID 38837897, 2024). "Our findings show that SCNAs adjust the regulatory landscape of neuroblastoma toward dysregulation of key cancer pathways and that copy-number gains effectively upregulate TERT in tumors with CTM, with highest telomerase expression found in tumors with both TERT activation and copy-number gains." (PMID 39635126, 2024). "Indeed, similar to that in developing sympathetic ganglion cells, the TERT promoter in MYCN-amplified neuroblastoma cells shows active chromatin marks and DNA methylation of the TERT gene body." (PMID 38837897, 2024). "Here, we analyzed DNA methylation at the TERT promoter and found that all neuroblastoma samples contained approximately 1.5 kb of hypomethylated DNA spanning from nucleotides −694 to +758 relative to the TERT gene transcription start site (TSS) and overlapping the TERT promotor region." (PMID 38837897, 2024). "The epigenetic landscape of the TERT locus is unique in neuroblastoma." (PMID 38837897, 2024). "Strikingly, neuroblastomas with long telomeres display DNA CpG hypomethylation and enrichment of the chromatin repressive mark H3K27me3 that extends for tens of kilobases around the TERT locus and includes neighboring genes." (PMID 38837897, 2024). "Next, we wanted to study the control of TERT expression in MYCN-amplified neuroblastoma cells." (PMID 38837897, 2024). "According to the findings 100, TERT activation in high-risk neuroblastoma is not just present in TERTSV+ and MYCN-amplified tumors." (PMID 36860927, 2023). "Paradigmatic is the observation that a subgroup of high-risk neuroblastoma patients having mostly unfavourable outcome were characterized by TERT rearrangements or by MYCN amplified tumours, both inducing massive transcriptional upregulation of the TERT gene." (PMID 38033865, 2023). "From our final list of 104 genes, 3 of them (MCM4, MCM7, and TERT) have already been found to be deregulated for their expression in high-risk neuroblastoma, but the great majority (101 genes) have not." (PMID 37759629, 2023). "The telomerase dependent pathway is activated through transcriptional upregulation of the gene telomerase reverse transcriptase (TERT) which is most frequently caused by amplification of the oncogene MYCN or by rearrangements of the TERT locus in neuroblastoma." (PMID 36153564, 2022). "Thus, combination therapy would likely be translated into the first clinical trial of a targeted therapy in patients with TERT-rearranged neuroblastoma." (PMID 35053227, 2022). "In line with our previous studies, we defined neuroblastomas as telomerase positive if TERT expression was above the threshold, if they harbored a TERT RA, or if they were MYCN amplified, as the latter had been shown to directly upregulate TERT expression in neuroblastoma." (PMID 36153564, 2022). "Since OTX015 is currently in phase II clinical trials and carfilzomib is an approved anti-tumor drug, the combination of OTX015 and carfilzomib is likely to be the first targeted therapy in the clinical trials for patients with TERT-rearrangement neuroblastoma." (PMID 36187481, 2022). "In this case, TERT overexpression is likely due to long-range genomic rearrangements, but not to promoter mutations in neuroblastoma." (PMID 35053227, 2022). "TERT rearrangements and ATRX mutations are also commonly observed in neuroblastoma." (PMID 34458583, 2021). "Additionally, other important genetic markers for neuroblastoma are mutations in ALK, PTPN11, TERT, ATRX, and amplification of MYCN." (PMID 34885007, 2021). "Surprisingly, several MYCN-amplified neuroblastomas also harbored TERT rearrangements." (PMID 34442335, 2021).